CTLA4 (cytotoxic T-lymphocyte associated protein 4)
Diseases named in the same sentence as CTLA4 in open-access papers (continued):
Sharing a sentence is not in itself a finding about the gene and the disease.
Autoimmunity (continued). "Administration of anti-CTLA-4 (blocking Ab) in mice that are susceptible to mercuric chloride (HgCl2) induced autoimmunity causes an increase in anti-nucleolar auto-antibodies." (PMID 16759382, 2006). "Cytotoxic T lymphocyte-associated protein 4 (CTLA-4), an inhibitory receptor regulating T-cell homeostasis and maintaining self-tolerance, has emerged as a key target for immune screening and therapeutics in autoimmunity and cancer." (PMID 41000380, 2025). "This has already been shown for COPA but is probably also the case in a few other monogenic forms of autoimmunity (e.g., APS1, IPEX, and CTLA4), in which relatively common autoimmunity-associated HLA alleles probably modify the risk of developing autoimmunity to specific autoantigens." (PMID 41608500, 2025). "Immune checkpoint blockade works by inhibiting checkpoint proteins, such as cytotoxic T-lymphocyte-associated protein 4 (CTLA-4) and programmed death-1 (PD-1)/PD-L1, which normally act as brakes on the immune response to prevent excessive activation and autoimmunity." (PMID 41007771, 2025). "As LRBA regulates CTLA4 trafficking, its deficiency has been linked to autoimmunity and lymphoproliferation, which could help explain the clinical heterogeneity among carriers of the same FAS variant." (PMID 40755914, 2025). "Despite autoimmunity being linked to its loss, our results indicate an up-regulation of CTLA4." (PMID 38542346, 2024). "Another possible mechanism involves the procedure of autoimmunity to kidney self-antigens following the loss of self-tolerance and potentiation of antigen recognition upon blocking the CTLA-4 or PD-1 pathway, which regulates immunity at peripheral and target organ levels, respectively." (PMID 39011500, 2024). "Interestingly, the susceptibility allele for autoimmunity at CTLA4 occurs in more than 50% of the healthy population, and appears to be enriched in patients with thyroid eye disease." (PMID 38108994, 2024). "Nevertheless, loss of function of the CTLA4 gene, whether induced by genetic knockout in vivo or inhibition in humans, is linked to widespread adverse effects related to autoimmunity across various tissues." (PMID 38451000, 2024). "Indeed, some IEI, such as CTLA-4 deficiency, present with cytopenias associated with both bone marrow failure and autoimmunity, making them “interface disorders”." (PMID 39475830, 2024). "Here, we have used the development of GvHD in NSG mice, using donors with HLA alleles predisposed to autoimmunity (psoriasis) to weight in favor of GvHD, as an endpoint to evaluate the relative potency of monoclonal and BiSpecific antibodies targeting PD-1 and CTLA-4 to break immune tolerance." (PMID 36936963, 2023). "As CTLA-4 is important in preventing autoimmunity, the unselective blockade of CTLA-4 could be the major cause of its related irAEs." (PMID 37106400, 2023). "The paradigmatic PID with multisystem autoimmunity is CTLA4 deficiency." (PMID 37350970, 2023). "Genetic association studies have suggested that polymorphisms in CTLA4 can impact both autoimmunity and the toxicity of ICIs, and that germline polymorphisms in CTLA4 may influence susceptibility to IRAEs." (PMID 36983597, 2023). "Variants of uncertain significance (VUS) in CTLA4 are frequently identified in patients with antibody deficiency or immune dysregulation syndromes including, but not limited to, patients with multi-organ autoimmunity and autoinflammation." (PMID 37740092, 2023). "The induced CTLA4 in the cytoplasmic domain may have caused the conversion of Treg cells to suppress autoimmunity due to the ‘cytokine storm’ of proinflammatory cytokines induced by FMD vaccination." (PMID 35764653, 2022). "Recent genetic association studies have revealed that polymorphisms in CTLA4 may modulate both autoimmunity and response and toxicity to ICIs." (PMID 35912205, 2022). "For instance, CTLA-4 deficiency is associated with immune dysregulation and aberrant autoimmunity." (PMID 36482486, 2022).
Autoimmunity (continued). "Studies using a mouse model mimicking the CTLA4 insufficiency in these patients, along with the findings from other groups using different animal model systems, have gathered robust evidence for a causal role of autoimmunity in tumorigenesis." (PMID 34235145, 2021). "It is noteworthy that PSGL-1 appears to regulate both CD4+ and CD8+ T cells comparably with respect to survival and function, and we do not find that Selplg-/- mice develop spontaneous inflammatory responses or signs of autoimmunity as do mice that are deficient in PD-1 and CTLA-4." (PMID 34326837, 2021). "In patients with CTLA-4 deficiency, surveillance for the risk of lymphomas is essential, and treatment of autoimmunity and lymphoproliferation comprehends the use of sirolimus and the biologic agent abatacept, a fusion molecule containing the extracellular domain of CTLA-4." (PMID 34682853, 2021). "Defects in CTLA‐4 trafficking due to LRBA deficiency cause profound autoimmunity in humans." (PMID 33960403, 2021). "The loss of Treg or the loss of CTLA‐4 specifically from Treg in mice triggers fatal autoimmunity." (PMID 33960403, 2021). "ICIs enhance the anti-cancer immune response by inhibiting the cytotoxic T-lymphocyte-associated protein 4 (CTLA-4) or by inhibiting the programmed cell death protein 1/programmed death-ligand 1 (PD-1/PD-L1) pathways that have a physiological role in preventing autoimmunity." (PMID 34338882, 2021). "This high degree of polymorphism in the canine CTLA4 promotor has the potential to impact on protein expression, which may, in turn, influence its immune regulatory function and susceptibility to autoimmunity." (PMID 32835228, 2020). "In addition, as an immune tolerance critical regulator, the loss of expression of CTLA-4 in animal models is lethal shortly post-birth owing to extensive proliferation of lymphocytes and autoimmunity." (PMID 32174961, 2020). "CTLA4 is an important regulator of T cell function and polymorphisms/mutations in CTLA4 have been associated with a number of autoimmune phenotypes in both humans and rodent models of autoimmunity." (PMID 32835228, 2020). "In this regard, future application of TSA and/or FPRP to updated meta-analyses could be of value for conclusive demonstration of CTLA-4 rs231775 as susceptibility risk factor for autoimmunity and cancer." (PMID 32732985, 2020). "The CTLA4 SNP has a protective effect, and the major allele G is associated with autoimmunity." (PMID 32328064, 2020). "Tumor immunity mainly involves in T cells and dendritic cells (DCs), and exploits immune checkpoints, which are normally critical for the prevention of autoimmunity, such as cytotoxic T lymphocyte-associated antigen 4 (CTLA4, CD152) and programmed cell death protein 1 (PD-1)." (PMID 32943996, 2020). "While mutations in LRBA and CTLA4 have phenotypic variance thought to be due to incomplete penetrance and epigenetic changes, a common finding in these patients is hypogammaglobulinemia and early onset severe autoimmunity." (PMID 31921101, 2019). "Polymorphisms in CTLA-4 may alter its functionality such that the activation of T cells cannot be inhibited, resulting in a loss of immune tolerance and the occurrence of autoimmunity, making it vital that normal CTLA-4 activity be maintained." (PMID 31565653, 2019). "On the other hand, as selective reduction of the soluble form of CTLA-4 is associated with tissue-specific autoimmunity both in mice and humans, it is speculated that sCTLA-4 has a tissue- and/or a circumstance-specific regulatory role." (PMID 31061392, 2019). "However, a thorough understanding of CTLA-4 function at the molecular level is necessary in order to develop strategies to prevent the unintended autoimmunity that is frequently associated with systemic blockade of CTLA-4 activity." (PMID 31061392, 2019).
Autoimmunity (continued). "Given the marked response of P1 to Abatacept (CTLA-4-Ig) treatment enabling clinical disease remission, we hypothesized that autoimmunity in DEF6 deficiency may be linked to aberrant CTLA-4 regulation." (PMID 31308374, 2019). "Moreover, neutralization of CTLA-4 is associated with intestinal inflammation and autoimmunity in human cancer." (PMID 28561062, 2017). "Notably, the inhibitory functions of CTLA-4 on CD4+ T cells appear to be more important for the prevention of autoimmunity as CTLA-4-deficient CD8+ T cells are incapable of inducing autoimmune pathology in the absence of CD4+ T cells." (PMID 28443090, 2017). "CTLA-4 has long been associated with control of autoimmunity." (PMID 26596798, 2015). "Therefore, we tested genetic predisposition to the induction of autoimmunity as a potential prognostic factor by evaluating the HLA genotypes and selected polymorphisms in cytotoxic T-lymphocyte-associated protein 4 (CTLA-4) and FOXP3 genes." (PMID 26192408, 2015). "Furthermore, CTLA-4-deficient mice died early, about one month after birth, due to lympho-proliferative disease and autoimmunity." (PMID 24594636, 2014). "CTLA4-deficient mice have high lymphoproliferation and lethal autoimmunity." (PMID 25153088, 2014). "Additionally for CTLA4, considered a general autoimmunity susceptibility gene but with conflicting association results for JIA, we did not generate any evidence of replication." (PMID 23506417, 2013). "Our investigation into the association of CLTA-4 polymorphisms and the results of interferon therapy in a population where the occurrence of autoimmunity has been rigorously prospectively characterized, assumes that the predominant effect of CTLA-4 polymorphisms is upon T-cell responsiveness." (PMID 21044351, 2010). "An alternative possibility studied by us is that Th17 cells, an immune cell subset implicated in mediating autoimmunity and in chronic inflammatory conditions, may be modulated by CTLA4 blocking antibodies." (PMID 19457253, 2009). "Immune checkpoints, such as cytotoxic T-lymphocyte-associated protein 4 (CTLA-4) and programmed cell death protein 1 (PD-1), are inhibitory receptors expressed on immune cells that regulate immune responses to maintain homeostasis and prevent autoimmunity under physiological conditions." (PMID 40474230, 2025). "Thus, this increases the degradation of CTLA-4 and the risk of autoimmunity." (PMID 39247203, 2024). "Patients with inherited CTLA-4 deficiencies present with a range of clinical features including recurrent respiratory tract infections and increased risk of autoimmunity, while inherited PD-1 deficiency has been linked with early-onset autoimmunity and severe tuberculosis." (PMID 38077329, 2023). "Therefore, it is likely that polymorphisms that reduce CTLA4 expression or activity may cause excessive activation and proliferation of T cells, predisposing to autoimmunity." (PMID 33746952, 2021). "Similarly, heterozygous missense mutations in CTLA‐4 or mutations in the trafficking protein LPS‐responsive beige‐like anchor protein (LRBA) (which affects CTLA‐4 expression) both cause clinically significant autoimmunity." (PMID 33960403, 2021). "Since the initial report, approximately two decades ago, that engagement of CD28 enhances glycolysis but PD-1 and CTLA-4 decrease it, significant information has been generated which has linked metabolic reprogramming with the fate of differentiating T cell in health and autoimmunity." (PMID 32257420, 2020). "Indeed, depletion of Tregs in adult mice is associated with rapid-onset autoimmunity, which might explain at least some of the effects for the off-target autoimmunity observed with CTLA4-blocking Abs." (PMID 28646041, 2017). "However, note that in humans, haploinsufficiency of CTLA4 is associated with significant autoimmunity, so blockade of CTLA4 could act synergistically with Treg depletion to promote the CD4-driven autoimmunity seen in mice and humans lacking Tregs." (PMID 28646041, 2017).
Autoimmunity (continued). "Hence, we postulated that, under most cases of spontaneous autoimmunity, alleles associated with reduced CTLA-4 function and/or expression could lead to increased activation of T cells thereby triggering autoimmunity." (PMID 25121088, 2014). "Here, we describe the first case of homozygous CTLA-4 deficiency (CTLA4 S172P/S172P ), presenting with early-onset autoimmunity, lymphoproliferation, and growth failure." (PMID 42273361, 2026). "Heterozygous loss-of-function CTLA4 variants cause CTLA-4 haploinsufficiency with autoimmune infiltration (CHAI), a disorder manifesting with a combination of autoimmunity and immunodeficiency." (PMID 41608053, 2025). "Immune checkpoints, such as PD-1 and CTLA-4 play a crucial role in maintaining self-tolerance and preventing autoimmunity." (PMID 39720481, 2025). "LRBA deficiency is strongly associated with immune dysregulation and is frequently accompanied by autoimmunity, particularly AICs, due to impaired CTLA-4 expression and regulatory T cell dysfunction." (PMID 40993545, 2025). "The role of quantitative differences in CTLA‐4 expression in controlling the development of autoimmunity is stronger in humans than mice." (PMID 40346769, 2025). "Conversely, inhibitory molecules like CTLA-4 and PD-1/PD-L1 limit excessive T-cell activity under normal conditions, protecting the body against inflammation and autoimmunity." (PMID 40723175, 2025). "The implications of this result via defects in Treg function in autoimmunity and manipulation of immune function by CTLA‐4‐Ig therapy will be discussed." (PMID 40346769, 2025). "Therapeutic targeting of ligands by CTLA4-Ig fusion proteins (Abatacept) or blocking CTLA4 with antibodies (e.g. Ipilimumab) have been used in autoimmunity and cancer to inhibit or invigorate CD28 signals, respectively." (PMID 40496752, 2025). "After investigation, CTLA-4 and its molecular therapy were found to have a crucial role in altering cancer pathogenesis, immunotherapy, and the pathogenesis of autoimmune disorders." (PMID 41395347, 2025). "The therapeutic rationale for ipilimumab centers on its selective inhibition of cytotoxic T-lymphocyte-associated protein 4 (CTLA-4), a critical immune checkpoint that downregulates T-cell activation to maintain immune homeostasis and prevent autoimmunity." (PMID 40940902, 2025). "Immune checkpoints such as PD-1, PD-L1, and CTLA-4 are physiological mechanisms that prevent autoimmunity but are often exploited by tumors to induce T-cell exhaustion." (PMID 41440517, 2025). "CTLA-4 plays a critical role in immune system homeostasis, particularly in regulating Treg function and preventing autoimmunity." (PMID 40943370, 2025). "Heterozygous loss-of-function variants in CTLA4 result in CTLA-4 haploinsufficiency with autoimmune infiltration (CHAI), characterized by immune dysregulation and autoimmunity." (PMID 41608053, 2025). "This has potential clinical applications; soluble CTLA-4 can be used to dampen T cell immune responses, thereby preventing excessive immune responses and autoimmunity." (PMID 38892300, 2024). "ICIs interfere with cell cycle checkpoint regulators like cytotoxic T-lymphocyte-associated protein 4 (CTLA-4) and programed cell death protein 1 (PD-1), which normally downregulate T-lymphocyte activation and promote self-tolerance to avoid autoimmunity." (PMID 39408897, 2024). "Although both CTLA‐4 and PD‐1 play important roles in autoimmunity, PD‐1 has been shown to play an especially important role in the development of autoimmune T1DM by inhibiting the expansion of autoreactive T cells." (PMID 39560155, 2024). "In preclinical mouse models, inhibition or genetic deletion of CTLA-4 and PD-1 leads to autoimmune disorders." (PMID 38318190, 2024). "In AIT, CTLA-4, functioning as a regulatory factor mediating T cell tolerance and autoimmunity, exhibits dysfunction that indirectly results in an elevated secretion of thyroid autoantibodies." (PMID 39314521, 2024).
Autoimmunity (continued). "Because Foxp3YFP-Cre crossed with Ctla4fl/fl animals to generate Treg-specific CTLA-4 conditional knockouts develop lethal autoimmunity at ∼7 wk of age as described, we were unable to subject them to a 12-wk alcohol protocol." (PMID 38226924, 2024). "Although the mechanisms by which CTLA-4 achieves its critical functions in immune homeostasis are highly debated, CTLA-4 indisputably safeguards against autoimmunity during the immune system’s beneficial antitumor and antipathogenic responses." (PMID 38312352, 2024). "This is best evidenced by the emergence of spontaneous autoimmunity in CTLA-4– and PD-1–knockout murine models." (PMID 38226621, 2024). "Under normal physiological circumstances, PD-1 and CTLA-4 prevent autoimmunity and curb immune activation to safeguard against unwanted inflammation." (PMID 38375475, 2024). "Overall, CTLA-4 and PD-1 are pivotal in maintaining peripheral tolerance and controlling the development of inflammation and autoimmunity." (PMID 39247203, 2024). "On the other hand, the expression of CTLA-4 on the surface of Tregs is an important factor in avoiding autoimmunity and regulating the proper function of APCs and naïve T cells." (PMID 38892453, 2024). "On the other hand, the CTLA‐4 is a co‐inhibitory molecule that plays a critical role in dampening immune responses to avoid autoimmunity, by suppressing T‐cell activation, proliferation, and cytokine production." (PMID 38883218, 2024). "CTLA-4 is essential for avoiding autoreactivity and its absence in humans leads to immunological dysregulation and PID-associated autoimmunity." (PMID 37189748, 2023). "Immune self-tolerance in humans is partly maintained by the inhibition of auto-reactive T cells through CTLA-4 and the PD-1/PD-L1 pathway, and PD-1 and CTLA-4 polymorphisms are associated with various autoimmune conditions." (PMID 38152395, 2023). "Physiologically, well known or traditional immune checkpoints (ICs), such as CTLA-4 and PD-1, are in place to promote tolerance to self-antigens and prevent generation of autoimmunity." (PMID 37345111, 2023). "The pathomechanism of autoimmunity in this monogenic disease is well-understood as CTLA4 is a major negative regulator of T cell activation in the immune synapse." (PMID 37350970, 2023). "Foxp3+ Tregs effectively reduce autoimmunity in vivo via CTLA4-dependent regulation of the autophagic processes in DCs." (PMID 37189748, 2023). "The patient with CTLA4 deficiency had ongoing gut inflammation despite full donor chimerism, and the patient with IPEX syndrome had mixed chimerism and relapse of autoimmunity." (PMID 37779531, 2023). "It is often used as an immunosuppressive agent in CTLA-4 haploinsufficiency and LRBA deficiency where it can improve both lymphoproliferation and autoimmunity, especially enteropathy." (PMID 37702894, 2023). "The cytotoxic T-lymphocyte-associated antigen 4 (CTLA-4), the key immune checkpoint and target gene of miR-155, plays a key regulatory role in mediating self-tolerance, preventing autoimmunity, and protecting tissues from immune attack." (PMID 36874964, 2023). "Organ-specific autoimmunity is common with monoclonal antibody blockade of CTLA-4 or PD-1/PD-L1 pathways." (PMID 38000024, 2023). "Expression of CTLA-4 mRNA in the orbital tissue of patients with severe TED is lower than in that of those with mild TED, supporting the involvement of CTLA-4 in TED autoimmunity." (PMID 38202079, 2023). "CTLA-4 plays an essential role in attenuating T-cell responses, preventing immune deregulation, inducing immune tolerance, and controlling autoimmunity." (PMID 36949956, 2023). "Polymorphisms in the CTLA-4 locus, such as CTLA-4 + 49 G/A, CT60, −1661A/G, and many more, have long been associated with autoimmunity." (PMID 37497212, 2023).